AFP (alpha fetoprotein)
Diseases named in the same sentence as AFP in open-access papers (continued):
Sharing a sentence is not in itself a finding about the gene and the disease.
tumor (continued). "We then investigated the correlations between EOGT/CD31 and HCC progression, including tumor staging, vascular invasion, liver fibrosis, Child–Pugh score, and AFP value." (PMID 35069551, 2021). "The variables used in the model were those that were known to have a prognostic impact after LT for HCC: number of tumor nodules, size, last AFP value available before LT and the presence of microscopic vascular invasion (mVI)." (PMID 34063501, 2021). "Three tumor biomarkers that widely used in clinical diagnosis, alpha-fetoprotein (AFP), CEA and carcinoma antigen 125 (CA125), were chosen to validate the proposed system for the simultaneous detection of multiple biomarkers." (PMID 33804983, 2021). "Clinically, previous studies have shown that posttransplant cancer recurrence and metastasis are significantly correlated with many factors, including tumor size and number, microvascular invasion, elevated AFP level and poorly differentiated tumor grade." (PMID 34966679, 2021). "One of the biomarkers of tumor processes in the liver is a change in the level of alpha-fetoprotein (AFP)—plasma protein produced by the yolk sac and the fetal liver during fetal development." (PMID 34884942, 2021). "Although AAR was also correlated with the tumor size in AFP‐NHCC, and there was a difference in the AUROC for each ratio (AUROC: 0.533 vs. 0.808 vs. 0.873), AAR exhibited a smaller AOC than the other ratios." (PMID 34145988, 2021). "The level of AFP elevation correlates with HCC tumor size, portal vein tumor invasion, treatment response, and post-transplant recurrence of HCC, making it an important prognostic and predictive biomarker." (PMID 33418899, 2021). "It was present more in moderate differentiation, Edmonson-Steiner histological grade 2 and grade 3 (p < 0.05, Chi-square), but it was not related with etiology, tumor size, Child–Turcotte–Pugh (CTP) and BCLC class, AFP level, and tumor recurrence." (PMID 34679523, 2021). "In case 1, the patient had normal liver function and tumor marker, AFP and PIVKA-II were within the normal ranges which can be considered to be low risk for HCC except for a dynamic CT study showing a tumor with an HCC-like enhancement pattern." (PMID 33555457, 2021). "Apart from tumor morphology, however, serum AFP has been widely recognized as a surrogate of tumor biology and is considered a strong predictor of outcomes among patients with HCC." (PMID 33670174, 2021). "The two-year OS rates were also significantly different according to the median tumor size (≥5 vs. <5 cm: 41.8% vs. 69.6%; p = 0.011) and the AFP level (≥400 vs. <400 ng/mL: 22.7% vs. 51.9%; p < 0.001)." (PMID 34684036, 2021). "Tumor-derived AFP impairs the differentiation and T-cell stimulatory activity of human dendritic cells." (PMID 33966049, 2021). "These associations suggest that treatment algorithms should be developed beyond the currently used tumor burden, extra-hepatic disease, and AFP biomarker." (PMID 34966854, 2021). "Serum AFP level is acknowledged as one of the most valuable serum tumor marker on diagnosis, evaluating prognosis and supervising recurrence of HCC." (PMID 33783988, 2021). "The findings showed that antiviral history, Child-Pugh class, tumor number, tumor size, γ-GT, and AFP were adverse parameters for post-recurrence survival." (PMID 34976804, 2021). "All cases were evaluated for tumour markers such as α-fetoprotein (AFP), carbohydrate antigen 19-9 (CA19-9), and carcinoembryonic antigen (CEA)." (PMID 34359670, 2021). "In the training group, the FOXP4-AS1 level in HCC samples was associated with age (P = 0.001), alpha-fetoprotein (AFP) (P = 0.002), and tumour diameter (P < 0.001)." (PMID 33604387, 2021). "Level of AFP ˃400 μg/mL index tumor size ˃5 cm and vascular invasion have been shown to strongly associate with extrahepatic metastases in HCC, especially when combined with into multi-parametric metastasis prediction criterion." (PMID 33562077, 2021).
tumor (continued). "Age >60 years, presence of EHM, main tumor size ≥10 cm, multiple tumors, higher AFP level, CPC B or C, and performance status ≥2 were significantly associated with higher mortality (all p < 0.05)." (PMID 33919745, 2021). "For the test cohort, elevated AFP levels and larger tumor sizes (>30 mm) were more prevalent in the MVI positive population (both p<0.05)." (PMID 34307168, 2021). "As far as oncological variables were concerned, surveilled patients presented an overall lower tumor burden and significantly lower levels of AFP." (PMID 33672751, 2021). "The AFP, maximal tumor size, microvascular invasion, tumor differentiation and SPATS2 expression were correlated with DFS of HCC patients." (PMID 33391405, 2021). "The results showed significant differences in the expression of ZCCHC17 in different subgroups of AFP, histologic grade, tumor status, vascular invasion and pathological stage." (PMID 35071004, 2021). "Many factors influence survival in HCC patients, including size, the presence of PVT, degree of tumor differentiation, level of serum AFP, tumor responses to therapy, and the presence of specific anatomical (and thus molecular) subtypes of HCC." (PMID 33546234, 2021). "Patients whose AFP-specific T cell responses are positive or high should be followed up with closely to allow for the early detection of tumours." (PMID 34496797, 2021). "Human T cells were transduced with mouse TCR specific for HLA-A2/AFP complex and these engineered human T cells have been reported to specifically recognize HLA-A2+ AFP+ HepG2 tumor cells and produce effector cytokines." (PMID 34071188, 2021). "Cox regression analysis was performed with adjustment for established risk factors, including PVTT extent, age, sex, Child-Pugh, ECOG, tumor size, and AFP." (PMID 33961627, 2021). "CMTM6 expression was significantly correlated with high AFP level (P = 0.032), tumor size (P = 0.016), advanced TNM stage (P < 0.001), vascular invasion (P = 0.001), and lymph node metastasis (P = 0.030) in the MTM type but not in the non-MTM type." (PMID 32770259, 2021). "•We developed a model, based on tumor size cutoff of 3.7 cm, any tumor number, and AFP cutoff of 600 ng/ml; and compared it with other transplant criteria." (PMID 34295467, 2021). "AFP is a class of protein with immunosuppression that can reduce the proliferation rate of T lymphocytes and inhibit the activity of tumor cytokines." (PMID 34434234, 2021). "In the univariate survival analysis, tumor size, portal vein invasion, extrahepatic spread, ALBI, AFP, AST, albumin, NLR, PLR and AST/ALT ratio were associated with OS (p < 0.05 for all)." (PMID 34124139, 2021). "We mainly explored the underlying mechanisms involved mucin or scavenger receptors that interact with AFP, provide more evidence to support these receptors as tumor AFPRs, and establish a theoretical basis for targeting therapy of cancer." (PMID 33718192, 2021). "This new nomogram included serum AFP level, tumor number, and three gadoxetic acid-enhanced MRI features (arterial peritumoral enhancement, satellite nodule and peritumoral hypointensity at HBP)." (PMID 34094938, 2021). "The HAP score takes into account four parameters (ALB, TBIL, AFP, and tumor size) and is divided into four levels (HAP-A, HAP-B, HAP-C, and HAP-D)." (PMID 34745962, 2021). "The TGCTs initial diagnosis is performed by a doctor through physical examination, ultrasound and analysis of serum tumor marker increase, such as: alpha fetoprotein (AFP), human chorionic gonadotropin (hCG) and lactic dehydrogenase enzyme (LDH)." (PMID 32459453, 2021). "For example, if an HCC patient’s tumor diameter was 5 cm, AFP > 400 ng/ml, and TB > 23 umol/l, their total points were 116.5, and the corresponding MVI was about 80%; thus, the predicted probability of MVI in such a patient can be regarded as very high." (PMID 34234239, 2021).
tumor (continued). "The use of Salmonella to overexpress tumor antigens in cancer cells, such as Legumain, PCSA, AFP, etc., has also been shown to inhibit tumor growth effectively." (PMID 33717106, 2021). "Recent meta-analysis has revealed that circulating tumor DNA (ctDNA) can serve as an assistant tool when combined with alpha-fetoprotein (AFP) for HCC detection." (PMID 34187556, 2021). "In 2012, a multi-centre French study incorporated the AFP threshold, number of nodules, and the largest tumor diameter in a prognostic score." (PMID 34885087, 2021). "To realize low cost, high sensitivity, and rapid detection for the tumor biomarkers such as alpha-fetoprotein (AFP), herein, we developed an amplified MRS immunosensor via enzyme-mediated cascade reaction with a microfluidic chip." (PMID 34124008, 2021). "Percutaneous biopsy is necessary for diagnosis if the tumor is unresectable, and serum AFP and HCG levels are normal." (PMID 34713845, 2021). "Patient selection in our center is based on tumor biomarkers, including AFP and PIVKA-II levels and 18F-FDG PET positivity." (PMID 34203396, 2021). "The optimal selection of patients for downstaging protocols includes an assessment of tumour burden, liver function, and surrogate markers for tumour biology, including alpha-fetoprotein." (PMID 34944957, 2021). "The covariates adjusted for PFS were tumor number, tumor extent, bilirubin, and Child–Pugh score, whereas those adjusted for OS were maximal tumor size, tumor number, tumor extent, bilirubin, Child–Pugh score, and AFP." (PMID 34685437, 2021). "Serum AFP is a well-established marker of tumor aggressiveness and has been used in clinical practice to screen high-risk patients, as well as in informing prognoses following primary HCC treatment." (PMID 33670174, 2021). "Songlin et al33 revealed the association between AFP and clinicopathological features of HCC, including Child‐Pugh grades and tumor size, which was consistent with our findings." (PMID 34145988, 2021). "The combination of AFP and other traditional tumor markers (TTMs) for the diagnosis of HCC is a possible strategy." (PMID 34394775, 2021). "AFP is still the most widely used tumor markers for HCC, and our present study and previous studies have confirmed its prognostic value in the recurrence of HCC." (PMID 34403527, 2021). "Our final nomogram integrated five independent risk factors for RFS of stage B HCC patients who received PA-TACE, including AFP, tumor size, tumor differentiation, tumor number, and MVI." (PMID 34745962, 2021). "On the other hand, a negative correlation was established between the expression of HMGB1 and tumor marker (alpha-fetoprotein (AFP))." (PMID 34583662, 2021). "Strikingly, data from The Cancer Genome Atlas (TCGA) database showed that the expression of FBXO45 was significantly correlated with AFP, tumor differentiation, tumor stage, and TNM stage." (PMID 34779401, 2021). "A nomogram incorporating Edmondson–Steiner classification, clinical TNM stage, tumor size, tumor capsule, tumor margin, AFP, and tumor number was constructed for MVI prediction." (PMID 35096577, 2021). "Largest tumor size >3.7 cm [HR:2.6, P = 0.02], and AFP > 600 ng/ml [HR:4.7, P = 0.001] were independent predictors of recurrence." (PMID 34295467, 2021). "When compared to AFP, there was improved cancer detection for all tumor sizes, especially small lesions." (PMID 34206321, 2021). "Traditional tumor staging and tumor markers such as AFP and carcinoembryonic antigen (CEA) are still the most common indicators of tumor prognosis and treatment." (PMID 34335239, 2021). "Significant variables included tumor size (p<0.0001), uninodular versus multinodular presentation (p<0.0001), and alpha 1 fetoprotein (AFP) levels (p=0.002)." (PMID 34644732, 2021). "A repeat MRI scan demonstrated that his tumor had decreased in size and his AFP levels dropped markedly but were still above the normal range." (PMID 36284916, 2021).
tumor (continued). "Although the endoscopic hemostasis delayed subsequent treatment and AFP level was elevated, the tumor and emboli of the left portal vein showed complete necrosis after the second cycle of triple combination therapy." (PMID 34868921, 2021). "Of those other predictors, we identified that AFP of > 169 ng/mL followed by an initial tumor size of 1.8 cm and an albumin threshold of 3.6 g/dL were the best discriminators of “slow” vs. “fast” TGR." (PMID 34966854, 2021). "Multivariate analysis revealed that alpha-fetoprotein (AFP) > 200 ng/mL (p = 0.021), number of tumors (p = 0.001), and tumor stage (p = 0.007) were independent prognostic factors for DFS." (PMID 34666694, 2021). "Cumulative plots and bar charts of sensitivity for groups within selected tumor size ranges show that the test has improved cancer detection compared to AFP for all tumor sizes and independently of the chosen tumor size threshold." (PMID 34206321, 2021). "A comparison of clinical characteristics between the two groups revealed that AFP and tumor size were significantly different between the groups, but not other characteristics." (PMID 33675149, 2021). "LLV patients with HCC were characterized by smaller tumor size, less serious liver injury, and lower AFP levels compared to patients with HBV DNA ≥ 2000 IU/mL." (PMID 34649509, 2021). "Our study emphasises the importance of tumour-related factors and hepatic reserve in influencing survival in both the entire population studied and in those ≥75 years confirming that CTP class, tumour size and serum AFP are independent prognostic factors." (PMID 33071284, 2021). "Tumor sizes, AFP levels and CEUS LR-M were found to be significant independent predictors of MVI in HCC patients." (PMID 34307168, 2021). "Blood biochemistry examination, urinalysis, and tumor markers (alpha-fetoprotein [AFP], human chorionic gonadotropin [HCG], and lactate dehydrogenase [LDH]) showed no abnormal findings." (PMID 33541424, 2021). "The factors of treatment modality, type of PVTT, largest tumor diameter and AFP achieved a p value < 0.1 in the univariate analysis and thus entered the multivariate analysis." (PMID 34521375, 2021). "Tumor markers before surgery showed beta human chorionic gonadotropin (β-hCG) <1 and alpha-fetoprotein (AFP) 209 units (reference < 10)." (PMID 34053459, 2021). "The classical serum tumor markers used routinely in the management of testicular germ cell tumor (TGCT) patients—alpha fetoprotein (AFP) and human chorionic gonadotropin (HCG)—show important limitations." (PMID 34680375, 2021). "The CD8 staining was low in ICC tissues compared to paired peritumoral tissues, and patients with low tumour-infiltrating CD8 T cells often accompanied with Serum AFP, large tumor size and Lymphatic metastasis." (PMID 34149929, 2021). "Clinically, HALs are considered to be male dominant with an abnormal AFP level in the serum or expressed on tumor tissue." (PMID 33585692, 2021). "Conversely, the ability of baseline AFP to predict tumor response to Sorafenib is controversial, while AFP changes over treatment appear to be more informative." (PMID 34072309, 2021). "Missing data included 25 albumin, 11 total bilirubin, 12 AFP, 3 tumor size, 3 tumor number, and 27 MVI values." (PMID 34235600, 2021). "An increase in the AFP level promotes the proliferation of tumor cells and the formation of blood vessels and enhances the antiapoptotic effect of cancer cells." (PMID 34884942, 2021). "In univariate analysis, large tumor size, high AFP level, and ALBI-grade migration to grade 3 in acute or chronic phase after TACE were associated with PFS." (PMID 34503135, 2021). "Subgroup analysis showed the improvement of MVI detection under SPRING was especially pronounced in patients with tumor size ≧5 cm and AFP level ≧400." (PMID 34804920, 2021).
tumor (continued). "The levels of tumor markers, including α-fetoprotein (AFP), protein induced by vitamin-K antagonist-II (PIVKA-II), carcinoembryonic antigen (CEA), and carbohydrate antigen 19-9 (CA19-9), were all within the normal limits." (PMID 34542724, 2021). "Among these biomarkers, the majority of data are for alpha-fetoprotein (AFP), which is demonstrated to be a useful predictor of the risk of drop-out while on the waiting list for LT, the risk of tumor recurrence after LT and overall survival (OS)." (PMID 34638365, 2021). "The results obtained by combining the morphological characteristics of the tumor and the AFP values made it possible to develop selection criteria for LT that definitively exceeded those of Milan." (PMID 34501381, 2021). "As regards interventional therapy and cryoablation, three tumor markers (AFP, AFP‐L3, and GP73) also had significant differences (p < 0.05)." (PMID 34403527, 2021). "Detection of the tumor marker alpha-fetoprotein in the blood serum is widelyused in the diagnosis of malignancies." (PMID 34377560, 2021). "The data analysis showed that for the four tumor markers, including Hsp90α, Hsp90α had the highest sensitivity (95.7%), and AFP had the highest specificity (92.5%)." (PMID 34348726, 2021). "The univariate analysis revealed that the ALT, AFP, maximal tumor size, microvascular invasion, tumor differentiation and SPATS2 expression were correlated with OS of HCC patients." (PMID 33391405, 2021). "Criteria from Hangzhou, China, included HCC patients with total tumor diameter less than or equal to 8 cm or patients with total tumor diameter greater than 8 cm whose AFP level is less than or equal to 400 ng/mL." (PMID 34638395, 2021). "Tumour size, serum AFP levels, tumour capsules, intratumoral vasculature and necrosis were also related to the presence of MVI (p < 0.05)." (PMID 34692547, 2021). "Taking into account availability and expense, an equivalent BAA-BS model was established based on total bilirubin, albumin, AFP, BMI and largest tumor size." (PMID 33531992, 2021). "Further analysis was conducted focusing on the quantity and proportion of the three immunoliposomes capturing CTCs of HCC patients under different age, gender, tumor number, tumor size, AFP, BCLC stage, and PIVKA." (PMID 33726759, 2021). "Age >50, tumors located in different segments, multiple tumors, tumor size >10 cm, presence of macrovascular invasion, histological grade III, and PRO AFP ≥400 ng/ml were considered significant risk factors (p < 0.05) for RFS in univariate analysis." (PMID 33932132, 2021). "The results illustrated that the high expression of UCA1 positively correlated with serum AFP (χ2 = 3.921, p < 0.05), tumor size (χ2 = 5.591, p < 0.05) and distant metastasis (χ2 = 5.345, p < 0.05)." (PMID 33565716, 2021). "Similar to pre-treatment immuno-PET imaging, GTVs correlated with serum AFP concentration after therapy (R2 = 0.87), confirming its accuracy in measuring tumor volume after serial antibody exposure." (PMID 33580090, 2021). "In our limited number of cases with the largest tumor size over 8 cm, our data support this literature, with the exception of AFP level." (PMID 33754656, 2021). "RS = 0.96 × if male + 0.01 × largest tumor size (mm) + 0.88 × if PET-positive + 0.21 ln (AFP+1) + 0.17 × ln (PIVKAII) + 0.02 × NLR." (PMID 34203396, 2021). "Of particular note in our analysis, was the usefulness of combination GGT plus albumin in the low-AFP cohort, for whom there are few other validated tumor markers." (PMID 34540270, 2021). "It appears clear that the risk of failure of successful downstaging is related to both the tumor burden and to AFP serum levels at baseline." (PMID 34501381, 2021). "The multivariate analysis of the training dataset found preoperative total tumor volume (TTV) and alpha-fetoprotein (AFP) to be independent risk factors for MVI." (PMID 34503212, 2021).